IQSEC2 (IQ motif and Sec7 domain ArfGEF 2)
Description:
Is a guanine nucleotide exchange factor for the ARF GTP-binding proteins.
Synonyms: KIAA0522; BRAG1; IQ-ArfGEF; MRX1; MRX18; MRX78; NEDXSB; XLID1
Tractability: PROTAC: ubiquitination databases record sites on it; its protein half-life has been measured.
Gene: Protein-coding gene on chromosome X (53,225,828 to 53,321,350, reverse strand). Ensembl gene ENSG00000124313.
Subcellular location: Cytoplasm
Subcellular location (Human Protein Atlas): Lipid droplets; Vesicles
Gene Ontology:
Molecular function: guanyl-nucleotide exchange factor activity; protein binding; protein-macromolecule adaptor activity
Biological process: modulation of chemical synaptic transmission; positive regulation of synaptic transmission; regulation of AMPA glutamate receptor clustering; regulation of long-term synaptic depression; regulation of neurotransmitter receptor localization to postsynaptic specialization membrane; regulation of postsynaptic density assembly; regulation of postsynaptic neurotransmitter receptor internalization; positive regulation of long-term synaptic depression; positive regulation of synapse assembly; positive regulation of synaptic transmission, glutamatergic; regulation of ARF protein signal transduction
Cellular component: postsynaptic density; Schaffer collateral - CA1 synapse; postsynaptic density membrane; cytoplasm
Gene-disease validity (ClinGen):
ClinGen rates the evidence that IQSEC2 causes each of these diseases.
X-linked complex neurodevelopmental disorder (X-linked): Definitive. A complex neurodevelopmental disorder that is transmitted via X-linked inheritance, and is characterized by intellectual disability, autism and epilepsy.
Homologues: Orthologues: macaque IQSEC2 (99% identical), mouse Iqsec2 (99% identical), rat Iqsec2 (99% identical), pig IQSEC2 (99% identical), chimpanzee IQSEC2 (93% identical), guinea pig IQSEC2 (82% identical), rabbit IQSEC2 (77% identical), dog IQSEC2 (76% identical), zebrafish iqsec2a (55% identical), zebrafish iqsec2b (54% identical), tropical clawed frog iqsec2 (49% identical), Drosophila melanogaster siz (25% identical), and 5 more. Paralogues in human: IQSEC1 (43% identical), IQSEC3 (29% identical), ARFGEF1 (14% identical), ARFGEF2 (14% identical), GBF1 (13% identical), MON2 (12% identical), PSD (10% identical), PSD3 (10% identical), PSD4 (10% identical), PSD2 (9% identical), CYTH3 (8% identical), CYTH2 (8% identical), and 3 more.
Diseases named in the same sentence as IQSEC2 in open-access papers:
IQSEC2 is named in the same sentence as 43 diseases in open-access papers, as found by Europe PMC text mining. Sharing a sentence is not in itself a finding about the gene and the disease. The quoted sentences say what the papers report.
epilepsy (28 papers, 2015 to 2025). A brain disorder characterized by episodes of abnormally increased neuronal discharge resulting in transient episodes of sensory or motor neurological dysfunction, or psychic dysfunction. "Pathogenic mutations in the IQSEC2 gene result in epilepsy, cognitive dysfunction and autism spectrum disorder." (PMID 40427528, 2025). "Pathogenic variants in the X-linked IQSEC2 gene are associated with drug-resistant epilepsy, severe intellectual disability, and autism." (PMID 40943242, 2025). "Pathogenic human mutations in the IQSEC2 gene result in the triad of drug-resistant epilepsy, cognitive dysfunction and autism spectrum disorder." (PMID 40427528, 2025). "Knockdown of Arf6 in mice results in enhanced seizure susceptibility, while dysregulation of ARF6 via IQSEC2 pathogenic variants are associated with epilepsy, intellectual disability, and autism." (PMID 38862622, 2024). "Mutations in the IQSEC2 gene account for 2–5% of children presenting with severe intellectual disability, autism spectrum disorder and epilepsy." (PMID 36835332, 2023). "Variants in the IQSEC2 gene are associated with a rare form of intellectual disability (ID) and epilepsy (OMIM # 300522) in males and females." (PMID 37761403, 2023). "The condition is likely to be underdiagnosed when the current prevalence figures are compared to the observed frequency of IQSEC2 pathogenic variants in 2% of all patients with ID and epilepsy who underwent a whole exome sequencing analysis." (PMID 37761403, 2023). "Pathological mutations in the IQSEC2 gene are frequently seen in children presenting with intellectual disability, autism and epilepsy." (PMID 36835332, 2023). "Mutations in IQSEC2 account for approximately 2% of patients with ID and epilepsy referred for exome sequencing." (PMID 36902414, 2023). "Pathogenic variants in IQSEC2 account for approximately 2% of patients with ID and epilepsy referred for exome sequencing." (PMID 37761403, 2023). "The isoleucine–glutamine (IQ) motif and Sec7 domain-containing protein 2 (IQSEC2) gene is associated with neurologic disorders, including intellectual disability (ID), epilepsy, and autism." (PMID 36267700, 2022). "IQSEC2 has been implicated in X-linked neurodevelopmental disorders, such as intellectual disability (ID), epilepsy, and autism." (PMID 34685703, 2021). "Human genome studies have revealed that the IQSEC2 gene is associated with X-linked neurodevelopmental disorders, such as intellectual disability (ID), epilepsy, and autism." (PMID 34685703, 2021). "Recently, missense mutations in amino acid residue 350 of IQSEC2 associated with ID, epilepsy, and autism were described." (PMID 34535765, 2021). "Seventy different mutations in IQSEC2 that are associated with moderate to severe ID, epilepsy, and autistic traits have been described." (PMID 34535765, 2021). "In this study, we have employed a battery of social behavioral tests to characterize the deficits in social behavior exhibited by mice with a A350V mutation in the Iqsec2 gene, a mutation that is associated with epilepsy, ID, and ASD in humans." (PMID 33888678, 2021). "Children with disease-causing IQSEC2 mutations exhibit epilepsy, ID, autism, developmental regression, and language deficits." (PMID 34535765, 2021). "We have recently described an A350V mutation in IQSEC2 associated with intellectual disability, autism and epilepsy." (PMID 30842726, 2019). "Variants in IQSEC2, escaping X inactivation, cause X-linked intellectual disability with frequent epilepsy in males and females." (PMID 30206421, 2019). "This is in contrast to early truncating mutations in IQSEC2, which in females are associated with a more severe phenotype including infantile spasms, epilepsy, autistic features, Lennox Gastaut syndrome and Rett-like syndrome." (PMID 26793055, 2015). "IQSEC2 is an X-linked gene that is associated with intellectual disability, autism, and epilepsy." (PMID 36902414, 2023).
epilepsy (continued). "Multiple IQSEC2 mutations have been reported and may lead to global severe developmental delay and epilepsy." (PMID 36267700, 2022). "During this investigation, we explored the relationship between the genotype and phenotype of IQSEC2 mutations; to do so, we recruited seven children with pathogenic/likely pathogenic IQSEC2 mutations who were diagnosed with global developmental delay and/or epilepsy." (PMID 36267700, 2022). "A350V in IQSEC2 is a missense mutation identified in patients with ID, epilepsy, and autism." (PMID 34685703, 2021). "Essentially, all IQSEC2 mutations are associated with ID, and epilepsy, particularly in males." (PMID 34535765, 2021). "IQSEC2 is an X-linked gene which has been previously associated with intellectual disability (ID), autism and epilepsy with mutations in IQSEC2 accounting for approximately 2% of patients with ID and epilepsy referred for exome sequencing." (PMID 30842726, 2019). "Group 2—Intermediate epilepsy/metabolic disorders (Ion-channel and neuronal-excitability phenotype): This group comprised patients harboring variants in SCN2A, PAH, IQSEC2, and GNPAT." (PMID 41300846, 2025). "The phenotypic spectrum of IQSEC2-associated disorder includes X-linked epileptic encephalopathy and non-syndromic XLID with epilepsy." (PMID 38612920, 2024). "Several GEFs have been associated with NDDs, including IQSEC2 associated with X-linked ID, and variants in HERC126,76, TRIO77,78, ARHGEF979,80, and ARHGEF1081, reported in patients with ID, epilepsy, and/or autism." (PMID 37563198, 2023). "IQSEC2 is an X-linked gene that is associated with autism spectrum disorder (ASD), intellectual disability, and epilepsy." (PMID 33753721, 2021). "The resulting disruption of IQSEC2 was thought to contribute to ID, epilepsy, progressive spasticity, and microcephaly in that patient." (PMID 26793055, 2015). "Finally, there are genes, such as IQSEC2, CDKL5, and NEXMIF, whose alteration causes epilepsy in both sexes." (PMID 38328757, 2023). "Apart from IQSEC2 associated with X-linked intellectual disability, many variants in GEFs HERC127,76, TRIO77,78, ARHGEF979,80, and ARHGEF1081 have been reported in patients with intellectual disability, epilepsy, and/or autism." (PMID 37034680, 2023). "Variants detected in epilepsy-related genes (DEPDC5, CHD2, SCN8A and IQSEC2) have been reported in patients with SCN1A variants and were considered to contribute to blended phenotypes comprising features of the disorder associated with the epilepsy gene and Dravet syndrome." (PMID 38891831, 2024). "Pathogenic hemizygous or heterozygous mutations in the IQSEC2 gene cause X-linked intellectual developmental disorder-1 (XLID1), characterized by a variable phenotype including developmental delay, intellectual disability, epilepsy, hypotonia, autism, microcephaly and stereotypies." (PMID 36012761, 2022).
Intellectual disability (27 papers, 2015 to 2025). "Shoubridge and colleagues first reported in 2010 on four affected individuals with IQSEC2 variants and severe intellectual disability, autism spectrum disorder, and drug-resistant seizures." (PMID 40943242, 2025). "IQ motif and Sec7 domain 2 (IQSEC2) is an X-linked gene that is associated with intellectual disability and ASD." (PMID 39056071, 2024). "We isolated Muse stem cells from patients with an intellectual disability (ID) and mutations in the IQSEC2 gene (i.e., BRAG1 gene) and induced in vitro neuroglial differentiation to study cell commitment and the differentiation of neural lineages." (PMID 37048050, 2023). "Pathogenic loss-of-function variants in the IQ motif and SEC7 domain containing protein 2 (IQSEC2) gene cause intellectual disability with Rett syndrome (RTT)-like features." (PMID 37761403, 2023). "Mutations in the coding region of IQSEC2 have been identified in patients with intellectual disability (ID), epilepsy, and autism since 2008." (PMID 37048050, 2023). "IQSEC2 and Fragile X chromosome disease both cause intellectual disability, developmental delay, and autism." (PMID 36902414, 2023). "WGS also localizes the gains insertion site, which is crucial for variant interpretation, as exemplified by our patient with a SHH-KDM4C neo-TAD, or a duplication in TENM3 explaining intellectual deficiency upon disruption of IQSEC2 sequence." (PMID 34744167, 2022). "Pathogenic variants in IQ motif and SEC7 domain containing protein 2 (IQSEC2) gene cause a variety of neurodevelopmental disorders, with intellectual disability as a uniform feature." (PMID 35347702, 2022). "We and others have identified disease‐causing variants in IQSEC2 that invariably cause intellectual disability (ID), and frequent severe early‐onset seizures." (PMID 35347702, 2022). "Mutations in the IQSEC2 gene are associated with drug-resistant, multifocal infantile and childhood epilepsy; autism; and severe intellectual disability (ID)." (PMID 34535765, 2021). "Mutations in IQSEC2 cause intellectual disability (ID), which is often accompanied by seizures and autism." (PMID 31234416, 2019). "At least 70 different mutations have been described in the IQSEC2 gene all associated with moderate to severe intellectual disability, with variable seizures and autistic traits." (PMID 30842726, 2019). "Pathogenic loss-of-function variants in IQSEC2 in females with intellectual disability and other comorbidities." (PMID 31439632, 2019). "Clinical presentations of mutations in the IQSEC2 gene on the X-chromosome initially implicated to cause non-syndromic intellectual disability (ID) in males have expanded to include early onset seizures in males as well as in females." (PMID 31439632, 2019). "This review will summarize our current knowledge of the molecular basis of intellectual disability (ID) in individuals with mutations in the IQSEC2 gene and how compromised IQSEC2 function may be related to autism spectrum disorder (ASD)." (PMID 31234416, 2019). "In addition, mutations of KDM5C cause mental retardation, X-linked, syndromic, Claes-Jensen type [OMIM #300534] and mutations of IQSEC2 cause mental retardation, X-linked 1 [OMIM #309530]." (PMID 28414775, 2017). "Examples include SCN2A, IQSEC2, and ADSL, whose mutations are associated with seizures, motor delays, and severe intellectual disability." (PMID 41300846, 2025). "Mutations in IQSEC2 gene cause X-linked intellectual developmental disorder-1, XLID1, (MIM: #309530), preferentially characterized by moderate to profound intellectual disability, often accompanied by seizures and autism spectrum disorder (ASD)." (PMID 36012761, 2022). "In humans, mutations in the IQSEC2 gene are associated with ASD, intellectual disabilities, and epilepsy." (PMID 33753721, 2021).
Intellectual disability (continued). "Mutations in IQSEC2 were first described in families with non-syndromic XLID and affected males showed moderate to severe intellectual disability, seizures, autistic traits, and behavioral disturbances as our patients do." (PMID 31906484, 2020). "Demonstration that IQSEC2 can regulate AMPA trafficking may therefore provide a mechanistic link for the severe intellectual disability and abnormalities in social behavior associated with mutations in IQSEC2." (PMID 30842726, 2019). "Microduplications in patients with intellectual disability have been found which encompass three disease genes, TSPYL2, KDM5C, and IQSEC2." (PMID 36902414, 2023). "Duplications and deletions involving KDM5C, IQSEC2 and TSPYL2 that do not overlap with HUWE1, have also been shown to cause developmental delay, intellectual disability, behavioral disturbances and/or autistic features." (PMID 28414775, 2017). "Male patients all present with moderate to profound intellectual disability, significant delays or absent language and speech and variable seizures, consistent with the features in other reported cases and highlights the importance of the PH domain for IQSEC2 function." (PMID 35347702, 2022).
autism (16 papers, 2017 to 2025). Persistent deficits in social interaction and communication and interaction as well as a markedly restricted repertoire of activity and interest as well as repetitive patterns of behavior. "ID, seizure, autism and severe speech and language deficits phenotypes due to missense mutations in the IQSEC2 PH like domain." (PMID 35347702, 2022). "There is an emerging clinical picture of ID, epileptic encephalopathy with speech and language deficits and autism due to a broad range of variants in the IQSEC2 gene, including the missense variants in the PH domain that we report here." (PMID 35347702, 2022). "The social deficit is frequently observed in human patients with IQSEC2 mutations as a core symptom of autism." (PMID 34685703, 2021). "Due to this high level of comorbidity, it seems likely that IQSEC2-associated ID and autism share common biochemical abnormalities." (PMID 31234416, 2019). "Similarly, other autism candidate genes including NLGNs, IQSEC2, DOCK4, and STXBP5, are also implicated in AMPAR trafficking." (PMID 38316900, 2024). "We propose a model by which IQSEC2 acts in promoting neurotransmission highlighting aspects which may be disrupted by mutations in IQSEC2 resulting in ID and autism." (PMID 31234416, 2019). "Mutations in the IQSEC2 gene associated with ID are often accompanied by autism and/or epilepsy." (PMID 31234416, 2019). "The reason that only half of the mutations in IQSEC2 present with autism may be due to dosage effects or other variable pathology that occurs due to the stochastic nature of epileptic seizures." (PMID 31234416, 2019). "Sec7 activity and AMPA receptor recycling are presented as two targets, which may respond to drug treatment in IQSEC2-associated ID and autism." (PMID 31234416, 2019). "The IQSEC2 KO mice showed overgrooming, a sign for repetitive and compulsive behavior typical for autism." (PMID 34685703, 2021). "The IQSEC2 KO mice exhibited overgrooming and social deficits reminiscent of the symptoms of autism." (PMID 34685703, 2021). "The prominence of IQSEC2 in neuronal spine formation makes it a logical candidate in affecting autism." (PMID 31234416, 2019). "Here, we review neuronal IQSEC2 signaling with emphasis on those aspects likely to be involved in autism." (PMID 31234416, 2019). "Through enzyme activity, IQSEC2 activates ARF6, a member of the Ras superfamily to facilitate downstream remodelling of actin cytoskeleton, a site of convergence with other ID and autism genes." (PMID 31439632, 2019).
Epileptic encephalopathy (6 papers, 2017 to 2026). A condition in which epileptiform abnormalities are believed to contribute to the progressive disturbance in cerebral function. "Future work is warranted to dissect how variants in the PH domain of IQSEC2 interferes with the protein activity and determine how dysfunction in this domain leads to early‐onset epileptic encephalopathy and ID in affected individuals." (PMID 35347702, 2022). "One unclassified epileptic encephalopathy patient had two deleterious mutations: SCN8A inherited from his affected father (c.4324G > A, p.E1442K) and IQSEC2 (c.4246_4247insG, p.S1416fs)." (PMID 30185235, 2018). "The IQSEC1 and IQSEC2 proteins are Ca+/CaM-regulated synaptic proteins that can activate all members of the ARF GTPase family and are mutated in neuronal developmental disorders including X-linked intellectual disability with early onset epileptic encephalopathy." (PMID 38072052, 2024).
autism spectrum disorder (5 papers, 2017 to 2025). A spectrum of developmental disorders that includes autism, and Asperger syndrome. "It is interesting to note that an increase in the expression of the KCNA6 gene (which has a similar function) was previously observed in another autism spectrum disorder (ASD) model and in RNA extracted from the hippocampi of IQSEC2 model mice (data not shown)." (PMID 34535765, 2021).
Rett-like syndrome (5 papers, 2015 to 2026). "Missense and truncated mutations associated with Rett-like syndrome demonstrate a clustered distribution within the IQSEC2 protein." (PMID 42220997, 2026). "Genes, such as IQSEC2 and even KCNQ2 from the green node, are linked to these genes since both genes are involved in the Rett-like syndrome phenotype." (PMID 35813072, 2022).